MMP14 (matrix metallopeptidase 14)
Diseases named in the same sentence as MMP14 in open-access papers (continued):
Sharing a sentence is not in itself a finding about the gene and the disease.
breast carcinoma (continued). "Our observations advocate that the lumican-induced suppression of the expression of MMPs, and mostly of MMP-14, comes in agreement with its inhibitory effect in breast cancer cells migration." (PMID 28332606, 2017). "Together, these results highlight the potential of MMP-14 blockade to disrupt the immune suppressive TME in metastatic breast cancers." (PMID 28938563, 2017). "A lead antibody that inhibits the catalytic domain of MMP-14 (Fab 3369) was identified and treatment of MDA-MB-231 breast cancer cells with Fab 3369 led to significant loss of extracellular matrix degradation and cell invasion abilities." (PMID 28938563, 2017). "At present, the study on MCF-7 breast cancer cells shows that the cytoplasmic tail of MMP-14 is required for the binding of TIMP-2 to MMP-14 on the MCF-7 surface, and when these two form as a complex, this can induce the proliferation and migration of MCF-7." (PMID 28397744, 2017). "As expected, increased expression of MMP-14 leads to increased metastasis in cancer models, and also correlates with poor prognosis in human breast cancer patients." (PMID 28938563, 2017). "Similar effects of MMP-14 blockade in syngeneic 4T1 mammary tumors were observed, along with increased detection of cytotoxic immune cell markers." (PMID 28938563, 2017). "Transcription factors specificity protein 1, hypoxia-inducible factor 2 alpha, and Krüppel-like factor 8 have been identified as potent regulators of MMP-14 expression in prostate cancer, renal cell carcinoma, and breast cancer." (PMID 27259238, 2016). "In conclusion, high extra- and intracellular proteolytic activity as well as high expression of transmembrane Mmp14 are hallmarks of CD24+CD90+ TICs in the MMTV-PyMT breast cancer model." (PMID 27542270, 2016). "Both CD13 (FLS) and MMP14 (breast carcinoma and glioma cells) have been found in caveolae-enriched lipid rafts." (PMID 27658265, 2016). "High MMP-14 expression has been documented in most types of human malignancies, including colon cancer, breast cancer, ovary cancer, and skin cancer, and its elevated expression is associated with tumor invasion and metastasis." (PMID 27259238, 2016). "Dissemination of breast carcinoma cells is mediated by membrane type 1-matrix metalloproteinase (MT1-MMP/MMP14), the main invadopodial matrix degradative component." (PMID 27116935, 2016). "High expression of MMP-2 (P=1.5e−6), MMP-9 (P=0.027), and MMP-14 (P=0.00051) is predictive of lower RFS in chemotherapy treated for ER− human breast cancer patients." (PMID 28721370, 2015). "MMP-11 and MMP-14 immunohistochemistry was performed on serial sections of human breast cancer biopsies." (PMID 25081520, 2014). "In association with TIMP-2, MMP-14 is involved in MMP-2 activation, being also correlated with breast cancer progression." (PMID 22260435, 2012). "In vitro, they showed MMP-14 specific uptake into MDA-MB-231 breast cancer cells, which decreased significantly upon chemical MMP-14 inhibition." (PMID 27713270, 2010). "In breast cancer, highest expression of MMP-14 by RT-PCR was found in cases with lymph node metastases, poor clinical stage and larger tumor size." (PMID 16776850, 2006). "In our tumor bank, information for MMP-2 was available from 610 breast cancers, from 544 for MMP-14 and from 549 cases for TIMP-2." (PMID 16776850, 2006). "MT1-MMP (MMP-14) and stromelysin-3 (MMP-11) are two members of the MMP family of proteolytic enzymes that have been specifically implicated in breast cancer progression." (PMID 15272933, 2004). "Furthermore, MMP-14 (MT1-MMP) is also related to poor prognosis in breast cancer patients and increased metastatic potential in multiple cancer models." (PMID 40943584, 2025). "All this evidence suggests that MMP14/MT1-MMP could be regarded as a key marker of breast cancer progression, with its elevated expression in 3D models compared to 2D likely being influenced by the highly hypoxic conditions within the spheroid core." (PMID 41228316, 2025).
breast carcinoma (continued). "Given MMP14’s dual role in breast cancer metastasis and neuroinflammation through blood–brain barrier modulation, its dysregulation may indicate compromised neuroimmune competence in fish brain tissue during severe cold stress." (PMID 41007409, 2025). "Analysis performed in a cohort of over one thousand breast cancer patients showed that Crp2 expression positively correlates with expression of inflammatory genes such as the Urokinase plasminogen activator surface receptor (uPAR), Mmp-2 and Mmp-14." (PMID 38173933, 2023). "In addition to MMP14, IL-8 was also highly expressed in invasive breast cancer cells as compared with primary breast cancer cells." (PMID 37564207, 2023). "Moreover, antibody-mediated blockade of MMP14 decreased tumor progression in mammary tumor mouse models." (PMID 37654625, 2023). "Further studies may be undertaken to complement these histological findings via qPCR by investigating the expression of MMP-2 and other relevant MMPs such as MMP-14 in whole mammary tumours." (PMID 37297024, 2023). "Reduced MMP-14 expression in tumor-initiating cells from a breast cancer mouse model decreased the characteristics of tumor-initiating cells, delayed tumor onset, and decreased tumor volume, indicating that tumoral MMP-14 promotes tumorigenicity in vitro and in vivo." (PMID 36741729, 2022). "MMP-14 was expressed mainly in the stroma of PyMT-induced tumors, and MMP-14-deficient MMTV-PyMT tumors displayed remarkably reduced lung metastasis compared to wild-type tumors, indicating that stromal MMP-14 is required for lung metastasis in breast cancer." (PMID 36741729, 2022). "In contrast, other studies have reported that stromal MMP-14 plays a role in breast cancer." (PMID 36741729, 2022). "Evaluation of breast cancer patients and clinical data indicated that GABARAP was associated with the clinicopathology-related characteristics of malignancy and negatively correlated with the expression of MMP2 and MMP14." (PMID 33591943, 2021). "The mechanosensitive ion channel Piezo1, which activates in ECs the MMPs -2 and -14 and promotes translocation of MMP-14 to the plasma membrane, is highly expressed in breast cancer and gastric tumor cell lines where its inhibition and knockdown impede cell motility and migration." (PMID 35008569, 2021). "MMP-14 was identified as an important effector of the matrix-remodeling processes in breast cancer." (PMID 34204372, 2021). "Additionally, miR-9, miR-113a, and miR-181a-5p can bind to the 3′-UTR of MMP14 mRNA in the cytosol and reduce MMP14 translation in gliomas, lung cancer, and breast cancer cells, respectively." (PMID 34297054, 2021). "In addition, CAFs express MMP-14 and contribute to invasion and metastasis in a murine breast cancer model." (PMID 33379400, 2020). "Notably, the collagen receptor α2β1 integrin induces MMP-14 expression in fibroblasts and breast cancer cells." (PMID 33379400, 2020). "We previously reported that ABL kinases interact with and regulate the subcellular localization and function of membrane-bound MT1-MMP (MMP14) in breast cancer cells, however ABL activation in tumors in response to MSC-mediated intercellular signals has not been reported." (PMID 33119681, 2020). "In regions of hypoxia, however, NHE1 activity is reduced and NHE1 gene expression is reported to be low in basal type and triple negative breast cancers, whereas CAIX is expressed in over 50% of patients with this breast cancer subtype, a patient subset that also expresses MMP-14." (PMID 29517989, 2018). "In breast carcinoma, for instance, MMP14 overexpression correlates with poor prognosis." (PMID 30174795, 2018). "In particular in breast cancer, MMP14 expression is a marker of increased cell invasiveness." (PMID 29934628, 2018). "Moreover, PROX1 ectopic expression reduced the MMP14-dependent 3D invasiveness of breast cancer cells and angiogenic sprouting of blood endothelial cells in conjunction with MMP14 suppression." (PMID 29934628, 2018).
breast carcinoma (continued). "However, further work is required to confirm the role of MMP14 in the control of CAIX expression within these breast cancer cell lines." (PMID 28476026, 2017). "Furthermore, shERβMDA-MB-231 breast cancer cells treated with lumican exhibited reduced proteolytic activity of MMP-14 and expression levels of MMP-7." (PMID 28332606, 2017). "Further we conclude that the main contributors to extracellular proteolysis of murine breast cancer TICs are metalloproteases, such as Mmp14, Mmp2, and Mmp13 along with aspartic proteases, because treatment with TAPI-O and Pepstatin strongly reduced DQ-collagen cleavage." (PMID 27542270, 2016). "In addition, it also remained conflicting as to the influence of MMP-1, MMP-2, MMP-11, MMP-13 and MMP-14 expression on the survival of breast cancer patients." (PMID 26270045, 2015). "However, in our study we found MMP-14 mRNA to be equally expressed in normal breast and breast cancer tissue." (PMID 19531263, 2009). "In addition, several MMPs that contribute to the proteolysis of collagen-425,26, including MMP2, MMP3, MMP9, and MMP14, were upregulated in either lung fibroblasts exposed to breast cancer cell-conditioned media, or premetastatic lungs in metastatic primary tumor-bearing mice." (PMID 37903851, 2023). "However, the roles and functions of stromal MMP-14 in breast cancer remain unclear, and further studies are required to elucidate them." (PMID 36741729, 2022). "Moreover, a recombinant human IgG specific to MMP-14 (IgG 3A2) demonstrated inhibitory effects on the growth of the primary tumor and lung metastasis in the 4T1 highly metastatic, syngeneic, orthotopic model of breast cancer." (PMID 36741729, 2022). "Since previous studies indicate that MMP-14 can regulate the VEGF expression in breast cancer cells, and combining the evidence that VEGF participates in the angiogenesis, we hypothesized that sub-cytotoxic MJ might also influence the expression of VEGF in gastric cancer cells." (PMID 23394613, 2013). "Therefore MMP-14 mRNA could possibly be expressed on equal levels in breast cancer tissue and normal breast tissue." (PMID 19531263, 2009). "One possible reason might be a higher translational rate of MMP-14 in breast cancer tissue." (PMID 19531263, 2009). "Our data show that, of the three proteases studied, MMP-14 was most strongly associated with breast cancer prognosis but was not independent of HER-2/neu or uPA, which may limit its usefulness as a prognostic marker." (PMID 16776850, 2006). "Despite its association with several cancer types, including lung cancer, gastric cancer, breast cancer (BRCA), pancreatic carcinoma, and bladder cancer (BLCA), comprehensive analyses of MMP14 in CRC remain limited." (PMID 40352589, 2025). "Highlighted Article:We show that MCT4 and CD147 colocalize with MMP14 at invadopodia and intracellular sites of ECM degradation, and favor breast cancer cell invasion by stimulating ECM degradation." (PMID 38661040, 2024). "Additionally, we found that four of these sEV surface proteins (CTTN, FSCN1, ICAM1, MMP14) were exclusively present in sEVs from high invadopodia activity cells, which have previously been reported in sEVs that are preferentially secreted from invadopodia in breast cancer cells." (PMID 37014551, 2023). "For example, upregulation of MMP-14 was blocked by upstream PI3K-AKT dependent β-catenin accumulation, thereby inhibiting the invasion and migration of breast cancer cells." (PMID 36741729, 2022). "PTK7 expression in breast cancer was significantly positively correlated with COL1A1, FN1, WNT5B, MMP11, MMP14 and SDC1 in breast cancer." (PMID 34367983, 2021). "MMP-14, a member of the MMPs family, has been shown to cleave CD44 to promote migration of osteosarcoma, pancreatic and breast cancer cells." (PMID 34944493, 2021). "NHE1 also stimulates the expression of MMP-14 via ERK1/2 and p38-MAPK signaling in MDA-MB-231 breast cancer cells." (PMID 35008569, 2021).
breast carcinoma (continued). "Upon 16-day treatment with BI01002494 no specific increase in proliferation (cyclin D1/2, PCNA) or invadopodia (MMP14, PARP) markers is observed in either DU4475 or MDA-MB-468 breast cancer cell lines." (PMID 32292575, 2020). "MMP14 and integrin αVβ3 complexes are capable of activating MMP2 activity with the assistance of TIMP2 in breast cancer and melanoma cells." (PMID 32352029, 2020). "A key mediator of collective invasion is MT1-MMP (MMP-14), which accumulates at the invasive front of tumours and is upregulated on the surface of breast cancer invadopodia." (PMID 30909510, 2019). "In breast cancer cells, KLF8 also cooperated with FAK to enrich the active MMP14 on the cell surface to facilitate the metastasis of the cancer cells." (PMID 31624471, 2019). "CAIX stimulated the activation of MMP14 by supplying protons required for MMP14 catalytic activity, enhancing the degradation of type I collagen and stimulating MDA-MB-231 (breast carcinoma) invasion." (PMID 31810330, 2019). "In conclusion, these results show that PROX1 acts as a negative regulator of MMP14 expression and MMP14-dependent 3D invasion in multiple cells types, such as BEC and breast cancer cells." (PMID 29934628, 2018). "Myeloma cells, as well as breast cancers, express MMP14 (MT1-MMP), which releases membrane-bound Sema4D by proteolytic cleavage." (PMID 29971044, 2018). "The results suggest that signaling proteins affected by EGCG in breast cancer, which include JUN, FADD, NFKB1, Bcl-2, GNAO1, and MMP14, are involved primarily in cell death and survival; DNA replication, recombination and repair; and the cell cycle." (PMID 28713815, 2017). "Several nodes in this pathway emerged as potential direct targets of EGCG in breast cancer: JUN, FADD, NFKB1, Bcl-2, GNAO1, and MMP14." (PMID 28713815, 2017). "Seven over-expressed breast cancer genes, namely BCAR1, HSD17B1, MMP14, PLAU, SFRP2, SPP1 and VCAN, had increased promoter methylation and their promoters contained the tumor-specific hypermethylated A-6 or A-7 HMRs." (PMID 25706888, 2015). "Metformin was found to inhibit EMT by interfering with TGF-β regulation in renal and in breast cancer cells and by modulating AR translation as shown herein and other EMT effectors such as MMP14." (PMID 24484909, 2014). "For this reason, we first analyzed the mRNA expression levels of MMP-2, MMP-9, MMP-14, TIMP-1, TIMP-2, TIMP-3 and RECK, in the same panel of five human breast cancer cell lines, but now maintained in culture until achieving 80-90% confluence." (PMID 22260435, 2012). "Matrix metalloproteinase-1 was immunohistochemically detected in 88.3% of breast carcinomas, MMP-2 in 42%, MMP-7 in 87.4%, MMP-9 in 74%, MMP-11 in 89.3%, MMP-13 in 73.3%, MMP-14 in 90%, TIMP-1 in 95%, TIMP-2 in 87% and TIMP-3 in 82.3%." (PMID 17848954, 2007). "In vitro, MT1-MMP (MMP-14, membrane type-1-MMP) expression is higher in more invasive human breast cancer (HBC) cell lines, whilst in vivo its expression has been associated with the stroma surrounding breast tumours." (PMID 16430785, 2006). "The participation of the membrane-type MMPs such as MMP-14, -15 and -16 is improbable due to the ability of TIMP-1 to effectively block collagen dissolution by breast cancer cells." (PMID 15701164, 2005). "This may be connected with the metastatic process of breast cancer (activating matrix metalloproteinase 9 (MMP9) and matrix metalloproteinase 14 (MMP14))." (PMID 37108392, 2023). "Due to their solid digesting function, the matrix metalloproteases MMP1, MMP11, MMP14, and MMP16 might confer invasiveness to breast cancer cells through the Zn2+-bound ZEB1." (PMID 36910659, 2023). "Similarly, CpG hypermethylation at MT1-MMP (MMP-14) and MMP-2 promoter sites decreased the migration of MCF-7 breast cancer cells." (PMID 38069210, 2023).
breast carcinoma (continued). "Moreover, it was found that migration and invasion of breast cancer cells induced by BMP also correlate with increased expression of metalloproteinases, namely MMP-2, MMP-9 and MMP-14." (PMID 36139691, 2022). "Due to the plasticity of invasion, it was reported that also the epithelial MCF-7 breast cancer cells, which do not show an evident MMP-14 expression, are indeed able to invade a lower dense collagen network collectively." (PMID 36551219, 2022). "MMP-14 expression in MICs is also a negative prognostic factor for relapse-free survival in breast cancer." (PMID 36741729, 2022). "In addition, in another study of selective MMP-14 inhibition, the authors created a mutant TIMP that blocked the collagenase activity of MMP-14 in cell culture models of breast cancer and fibrosarcoma." (PMID 34204372, 2021). "Co-expression analysis and gain- or loss-of-function of PTK7 in TNBC cell lines revealed that PTK7 participates in EGFR/Akt signaling regulation and associated with extracellular matrix organization and migration genes in breast cancer, including COL1A1, FN1, WNT5B, MMP11, MMP14 and SDC1." (PMID 34367983, 2021). "Moreover, TNFα activates the MAPK/ERK signaling pathway and subsequently promotes the migration of breast cancer cells through the upregulation of MMP9, MMP14, and MMP2 in the lipid rafts." (PMID 32986377, 2020). "Downregulation of MMP14 also reduces the formation of lung metastases without affecting primary tumor size in a mouse model of breast cancer." (PMID 31466240, 2019). "To test this, we chose HuAR2T, an HuVEC cell line, and MDA-MB-321, an invasive breast cancer cell line, both expressing high levels of MMP14, but no PROX1." (PMID 29934628, 2018). "Moreover, lumican achieved a striking decrease of the proteolytic activity of MMP-14 both in the highly-invasive MCF-7/SP10+ and in the aggressive MDA-MB-231 cells, rendering lumican as a critical inhibitor of breast cancer invasion and metastasis." (PMID 28332606, 2017). "Our network analysis also allowed us to identify several specific proteins that EGCG may help regulate in breast cancer, including JUN, FADD, NFKB1, Bcl-2, GNAO1, and MMP14." (PMID 28713815, 2017). "In breast cancers, activated Src-FAK signalling enriches the cell surface with active MMP14 to promote metastasis, thus indicating posttranslational modification and membrane localisation are essential in MMP14-mediated invasion." (PMID 26001294, 2017). "MMP-14 blockade led to increased iNOS+ cells and reduced CD206+ cells with the mammary tumors." (PMID 28938563, 2017). "Taken together, these results indicate that the E2F1-mediated expression of MMP2, MMP9, MMP14, and MMP15 might be repressed by KDM2A, eventually hindering the migration and invasion of breast cancer cells." (PMID 25029110, 2014). "Moreover, some reports recently suggested that expression of MMP14 downstream target such as MMP2 correlates with cancer progression in colon and breast cancers 11–40." (PMID 24156018, 2013). "We analyzed the expression levels of MMP-2, MMP-9 and MMP-14 and their inhibitors (TIMP-1, TIMP-2 and RECK) by quantitative RT-PCR (qRT-PCR) in five human breast cancer cell lines presenting increased invasiveness and metastatic potential, 72 primary breast tumors and 30 adjacent normal tissues." (PMID 19144199, 2009). "Here, we propose a more comprehensive approach by analyzing the expression levels of several MMPs (MMP-2, MMP-9 and MMP-14) and MMP inhibitors (TIMP-1, TIMP-2 and RECK) in different models (five human breast cancer cell lines, 72 primary breast tumors and 30 adjacent normal tissues)." (PMID 19144199, 2009). "Here, we proposed a more extensive approach by analyzing the mRNA expression levels of different MMPs (MMP-2, MMP-9 and MMP-14) and MMP inhibitors by qRT-PCR (TIMP-1, TIMP-2 and RECK) in several models (five human breast cancer cell lines, 72 primary breast tumors and 30 adjacent normal tissues)." (PMID 19144199, 2009).